GAD1 (glutamate decarboxylase 1)
Diseases named in the same sentence as GAD1 in open-access papers (continued):
Sharing a sentence is not in itself a finding about the gene and the disease.
Cerebral ischemia (4 papers, 2020 to 2023). Restriction of arterial blood supply to the brain associated with insufficient oxygenation to support the metabolic requirements of the tissue. "We investigated the impact of cerebral ischemia on the BDNF-related pathway in the hippocampus, focusing on GAD1, which is a GABA-associated factor." (PMID 33920851, 2021). "Cerebral ischemia suppressed GAD1 expression by decreasing hippocampal BDNF expression." (PMID 33920851, 2021). "Additionally, to further clarify the effect of brain ischemia in the hippocampus, we analyzed GAD1 mRNA levels in the hippocampus of tacrine-administered mice." (PMID 33920851, 2021).
cerebral palsy (4 papers, 2020 to 2025). A group of disorders affecting the development of movement and posture, often accompanied by disturbances of sensation, perception, cognition, and behavior. "To date, though GAD1 mutation has been widely cited as a cause of autosomal recessively inherited cerebral palsy, this kindred is the only reported example of CPSQ1 (OMIM 603513)." (PMID 33634263, 2021). "There is a single case described in the literature of an individual with cerebral palsy and a GAD1 variant." (PMID 32705143, 2020). "GAD1 codes for the enzyme responsible for catalyzing the production of gamma-aminobutyric acid from L-glutamic acid, and is associated with diseases such as cerebral palsy, spastic quadriplegic, and inherited congenital spastic tetraplegia." (PMID 31969651, 2020).
Epileptic encephalopathy (4 papers, 2020 to 2022). A condition in which epileptiform abnormalities are believed to contribute to the progressive disturbance in cerebral function. "The GAD1 gene with the greatest fold change was reported as a causative gene associated with syndromic developmental and epileptic encephalopathy." (PMID 35436926, 2022). "Our findings highlight an important role for GAD1 in seizure induction, neuronal and extraneuronal development, and introduce GAD1 as a new gene associated with developmental and epileptic encephalopathy." (PMID 32705143, 2020). "Here we describe a new syndromic developmental and epileptic encephalopathy caused by bi-allelic loss-of-function variants in GAD1, as presented by 11 patients from six independent consanguineous families." (PMID 32282878, 2020).
heroin addiction (4 papers, 2014 to 2024). "GAD1 is a glutamic acid decarboxylase related to glutamate-dependent acid resistance; candidate gene studies reported genetic variants associated with heroin addiction." (PMID 36745154, 2022). "A recent study also reported that genetic polymorphisms of the glutamate decarboxylase 1 (GAD1) gene were associated with heroin dependence." (PMID 25025424, 2014). "Glutamate decarboxylase 1 (GAD1) is an important factor in the glutamate metabolism network; it plays a crucial role in conditions such as attention deficit/hyperactivity disorder (ADHD), heroin addiction, early infantile epilepsy, and developmental delay." (PMID 38203806, 2024).
renal cell carcinoma (4 papers, 2014 to 2025). "Silencing GAD1 genes has been reported as a poor prognosis indicator for patients with renal cell carcinoma." (PMID 40227606, 2025). "Because of a report of GAD1 protein expression in a subset of renal cell carcinomas, we interrogated a recently published study of the clear cell subtype of renal cell carcinomas provided through the cBioPortal to determine if there were similar survival characteristics." (PMID 24551133, 2014).
glioblastoma (3 papers, 2019 to 2026). The most malignant astrocytic tumor (WHO grade IV). "Overexpression of GAD1 suppressed glioblastoma cell proliferation, colony formation, cell cycle progression, migration, and invasion, whereas knockdown of GAD1 promoted these phenotypes." (PMID 41844572, 2026). "The GSK3β inhibitor AR-A014418 effectively counteracted the effects of GAD1 knockdown, suppressing the enhanced proliferation, cell cycle progression, and invasion of glioblastoma cells, while also reducing the expression of p-GSK3β, β-catenin, Cyclin D1, and MMP9." (PMID 41844572, 2026). "Collectively, these results suggest that GAD1 inhibits the expression of Cyclin D1 and MMP9 via the p-GSK3β/β-catenin pathway, thereby impeding glioblastoma progression." (PMID 41844572, 2026). "For example, both glutamate decarboxylase 1 (GAD1) and Chitinase 3 Like 1 (CHI3L1/YKL-40) have been recently identified as targets of Notch inhibitors (alpha secretase and gamma secretase inhibitors) in treating glioblastoma stem cells." (PMID 30626092, 2019).
lung carcinoma (3 papers, 2016 to 2023). "Targeting the knockdown of GAD1 in COPD may attenuate the increased risk of lung cancer in COPD patients." (PMID 30361509, 2018). "A recent study has demonstrated that GAD1, independent of the GABA shunt, influences the growth of cancer cells in lung cancer tissues by controlling amino acid homeostasis." (PMID 37568704, 2023).
mental disorder (3 papers, 2012 to 2022). A disease that has its basis in the disruption of mental process. "Glutamic acid dehydrogenase GAD1, the key enzyme for the synthesis of the inhibitory and anxiolytic neurotransmitter GABA, is supposed to influence various mental disorders, including mood and anxiety disorders." (PMID 22662185, 2012).
oral cancer (3 papers, 2013 to 2024). "GAD1 knockdown inhibits the cellular invasiveness and migratory abilities of human oral cancer cells by regulating β-catenin translocation and MMP7 activation." (PMID 38553479, 2024). "GAD1 was overexpressed in OSCC-derived cell lines and new functions of GAD1 were related closely to cellular invasiveness and migration in oral cancer." (PMID 24261884, 2013). "GAD1 might play an important role in controlling tumoral invasiveness and metastasis in oral cancer." (PMID 24261884, 2013). "Kimura et al6 demonstrated that GAD1 promotes the cancer cell invasion and metastasis of oral cancer by inducing the nuclear translocation of β‐catenin and secretion of MMP7,15, 16, 17, 18, 19, 20 although the regulatory mechanisms of GAD1 in β‐catenin translocation remain unclear." (PMID 31207151, 2019).
oral squamous cell carcinoma (3 papers, 2013 to 2023). "GAD1 plays a crucial role and has been identified as a potential target for oral squamous cell carcinoma, due to its interaction with the Wnt/β-catenin/MMP7 pathway." (PMID 36814556, 2023). "Little is known about the relevance of GAD1 to oral squamous cell carcinoma (OSCC)." (PMID 24261884, 2013).
thymoma (3 papers, 2020 to 2022). A neoplasm arising from the epithelial cells of the thymus. "Another study, examining DNA methylation by bisulfite pyrosequencing, revealed significantly higher methylation levels of glutamate decarboxylase 1 gene (GAD1) in TC tissues, with GAD1 methylation exhibiting high sensitivity and specificity for discriminating between TC and thymoma." (PMID 35409405, 2022).
cocaine addicts (2 papers, 2012 to 2013). "Changes specific to cocaine addiction were the down-regulation of GAD1 and GAD2, genes that encode glutamic acid decarboxylase, the enzyme responsible for the majority of GABA synthesis from glutamate in the CNS." (PMID 22253714, 2012).
colon cancer (2 papers, 2023 to 2024). "Rather than serving as metabolic fuel or building blocks, GABA derived from lung and colon cancers activates GABABR to stabilize β‐catenin induced by the ectopic expression of GAD1." (PMID 37199392, 2023). "Gene expression of GABRB3, GABRG2, and GAD1 positively correlated with genes involved in the synthesis of PGE2 (PTGS2 and PTGES) as well as IL‐6 in human colon cancer." (PMID 38886975, 2024).
colorectal cancer (2 papers, 2023). A primary or metastatic malignant neoplasm that affects the colon or rectum. "However, recent studies have identified that GAD1 and GABA play active roles in non-neural systems, especially in promoting cancers, including oral, breast, gastric, prostate, and colorectal cancers." (PMID 36814556, 2023).
liver cancer (2 papers, 2019 to 2023). An epithelial or non-epithelial malignant neoplasm that arises from the liver. "Because hypermethylation‐associated overexpression of GAD1 was reported in colorectal and liver cancers, we reevaluated the results of the array‐based methylation status of each CpG site within CGI‐1‐4 around GAD1." (PMID 31207151, 2019).
neuroblastoma (2 papers, 2018 to 2024). Neuroblastoma (NB) is the most common solid, extracranial childhood tumor. "Culturing U87MG and mouse neuroblastoma (Neuro-2a) cells in low-glucose medium failed to induce changes in SIRT4 and GAD1 protein and mRNA levels, ruling out the possibility that the KD drives SIRT4 overexpression solely owing to its low carbohydrate content." (PMID 38346975, 2024).
renal carcinoma (2 papers, 2014 to 2023). A carcinoma arising from the epithelium of the renal parenchyma or the renal pelvis. "Based on our findings, miR-4284 is expected to affect the development and metastasis of renal cancer cells by directly targeting GAD1." (PMID 37568704, 2023). "Using previously published datasets characterizing gene expression in prostate and renal cancers, a potentially deleterious effect of GAD1 overexpression and GLUL underexpression on patient survival was identified." (PMID 24551133, 2014). "Overall, these results indicate that GAD1 is a direct target of miR-4284 in renal cancer cells." (PMID 37568704, 2023). "However, further studies are required to clarify the effects of miR-4284 and GAD1 on renal cancer cells with or without a GABA shunt." (PMID 37568704, 2023).
spastic cerebral palsy (2 papers, 2020 to 2021). A form of cerebral palsy wherein spasticity is the exclusive impairment present. "According to these observations and the consistency of the phenotype in our case series, we emphasize that GAD1 pathogenic variants should be considered the cause of a distinctive neurodevelopmental disorder instead of spastic cerebral palsy." (PMID 32705143, 2020).
teratocarcinoma (2 papers, 2008 to 2011). A germ cell tumor characterized by the presence of an embryonal carcinoma component and a teratoma component. "We focused on a molecule that blocked Wnt-induced reporter activity and also repressed Axin2 expression in 10T1/2 cells and SAX1 and GAD1 expression in teratocarcinoma cells induced with exogenous Wnt3a (data not shown)." (PMID 18698373, 2008).
bone fracture (1 paper, 2020). "Furthermore, we discovered that two genes coding for the GABA receptors GABBR2 and GLRA1 and the gene coding for glutamate decarboxylase GAD1, showed an association with total body BMD, and remarkably GABBR2 associated with bone fractures." (PMID 31969651, 2020).
brain glioblastoma (1 paper, 2024). A WHO grade IV malignant astrocytic tumor that arises from the brain, usually the cerebral hemispheres. "When GAD1 was overexpressed in U87MG (a human brain glioblastoma cell line) cells, it increased GABA levels; however, it failed to decrease glutamate levels, suggesting that GAD1 activity is more important for GABA/glutamate ratio than for glutamate levels." (PMID 38346975, 2024).
brain tumors (1 paper, 2023). "In particular, GAD1 has been studied for its association with various cancers, including brain tumors, because of its important role in metabolism via the GABA shunt." (PMID 37568704, 2023).
cataract (1 paper, 2025). Partial or complete opacity of the crystalline lens of one or both eyes that decreases visual acuity and eventually results in blindness. "Notably, these findings contrast with previous research where GAD-1 (Feeling nervous, anxious, or on edge) demonstrated the highest centrality value, and studies of cataract patients that recognized GAD-2 as central but did not identify GAD-4 as significant." (PMID 41050802, 2025).
clear cell renal cell carcinoma (1 paper, 2014). "Using The Cancer Genome Atlas, overexpression of the GABA synthetic enzyme, glutamate decarboxylase 1 (GAD1), was found to be associated with decreased disease free-survival in prostate adenocarcinoma and decreased overall survival in clear cell renal cell carcinomas." (PMID 24551133, 2014). "The correlation between GAD1 mRNA overexpression and decreased disease-free survival in prostate adenocarcinoma and overall survival in clear cell renal cell carcinoma prompted us to examine the potential role of GAD1 in NE metabolism." (PMID 24551133, 2014).
Constipation (1 paper, 2025). Infrequent or difficult evacuation of feces. "Specifically, CELNs treatment significantly upregulated GABAA R subunits (including α3 and β2) and GABA synthases (including GAD1) in colonic tissues, suggesting that GABA and its receptor system play pivotal roles in CELNs-induced constipation relief." (PMID 41282635, 2025).
developmental and epileptic encephalopathy (1 paper, 2022). An epilepsy associated with developmental impairment that may be due to either the underlying etiology or the superimposed epileptic activity, or both. "GAD1-expressing inhibitory neurons are associated with human developmental and epileptic encephalopathy." (PMID 36569494, 2022).
hepatocellular carcinoma (1 paper, 2023). A malignant tumor that arises from hepatocytes. "Furthermore, GAD1 influences GABA metabolism via the glutamine-glutamate/GABA cycle, which is important for hepatocellular carcinoma." (PMID 36814556, 2023).
HIV encephalitis (1 paper, 2016). "When HIV-positive subjects were sorted according to whether or not they had HIV encephalitis (HIVE) at autopsy, the mRNAs were significantly lower than HIV-negatives in the patients without and with HIVE both (by 26 and 23 % for GAD1, 21 and 27 % for GAD2, 20 and 24 % for GJD2)." (PMID 26829944, 2016).
Intellectual disability (1 paper, 2021). "Very recently, patients with intellectual disability with a null mutation of GAD1 were described for the first time." (PMID 33325157, 2021). "It is also noteworthy that all known patients with Gad1 null mutations exhibit mental retardation." (PMID 33325157, 2021).
Lymph node metastasis (1 paper, 2019). "Lymph node metastasis also tended to be more frequently observed in the positive GAD1 immunoreactivity group." (PMID 31207151, 2019).
melanoma (1 paper, 2024). A malignant, usually aggressive tumor composed of atypical, neoplastic melanocytes. "Mechanistically, BRAFV600E melanoma cells were found to overexpress the GABA-synthesizing enzyme GAD1, as compared to melanocytes and to produce GABA." (PMID 39201498, 2024). "Since the upregulation of GAD1 in human melanoma biopsies correlates with primary tumor-forming ability, GAD1 expression might be a useful prognostic marker to predict early tumor initiation from pre-cancerous moles." (PMID 39201498, 2024).
mesenchymal tumors (1 paper, 2017). "All three GABA related genes -- glutamate decarboxylase 1 (GAD1) and 2 (GAD2) and 4-aminobutyrate aminotransferase (ABAT) -- were lower in mesenchymal tumors, which in contrast showed higher IDO1 (indoleamine 2, 3-dioxygenase 1) and TDO2 (tryptophan 2, 3-diaxygenase)." (PMID 28245795, 2017).
metastasis (1 paper, 2013). The spread or migration of cancer cells from one part of the body (where they first appeared) to another. "In the clinical samples, GAD1 expression in the primary OSCCs was significantly (P < 0.05) higher than in normal counterparts and was correlated significantly (P < 0.05) with regional lymph node metastasis." (PMID 24261884, 2013).
metastatic cancer (1 paper, 2019). A carcinoma which has spread from the original site of growth to another anatomic site. "The authors unveiled the mechanism of this genetic shift, implicating increased GABA synthesis by metastatic cancer cells via methylation-dependent upregulation of glutamate decarboxylase 1 (GAD1) expression." (PMID 31396225, 2019).
nicotine dependence (1 paper, 2023). Physical and psychological dependence on nicotine.
non-alcoholic steatohepatitis (1 paper, 2023). "Specifically, TNFSF14 and GAD1 are highly expressed in HCC; STARD1 promotes the progression of non-alcoholic steatohepatitis to HCC via bile acids; DHRS4-AS1 ameliorates HCC by suppressing proliferation and promoting apoptosis via the miR-522-3p/SOCS5 axis." (PMID 36899918, 2023).
ovarian endometrioid adenocarcinoma (1 paper, 2013). An endometrioid adenocarcinoma arising from the ovary. "GAD1 is related closely to β-catenin expression by microarray analysis in ovarian endometrioid adenocarcinoma and Wilms’ tumor, whereas the functional interaction between GAD1 and β-catenin has not been demonstrated clearly." (PMID 24261884, 2013).
prostate adenocarcinoma (1 paper, 2014). "The robust concentration of GABA in PNEC cells coupled with previous findings that GABA shunt components, specifically GAD1, are enriched in PNEC cells relative to other prostate adenocarcinoma cells prompted us to use this cell line to investigate environment stress-induced modulation of GABA." (PMID 24551133, 2014).
pyridoxine-dependent epilepsy (1 paper, 2004). A rare neurometabolic disease characterized by recurrent intractable seizures in the prenatal, neonatal and postnatal period that are resistant to anti-epileptic drugs (AEDs) but that are responsive to pharmacological dosages of pyridoxine (vitamin B6). "Linkage of pyridoxine-dependent epilepsy has however been reported to 5q31.2-31.3, with GAD1 and GAD2 excluded." (PMID 15571623, 2004).
retinal ischemia (1 paper, 2018). A ischemic disease that involves the retina. "The downregulation of GAD1 and GAD2 may be associated with ischemic processes as decreased levels of GAD1 and GAD2 have previously been observed with retinal ischemia." (PMID 30366444, 2018).
spastic (1 paper, 2004). "Further investigation seems merited of the possibility that variation in the GAD1 sequence, potentially affecting glutamate/GABA ratios, may underlie this form of spastic CP, given the presence of anti-GAD antibodies in SPS and the recognised excitotoxicity of glutamate in various contexts." (PMID 15571623, 2004).
thyroid cancer (1 paper, 2024). "We found multiple instances of glutamate receptors (e.g., GRM1, 2, 4, 5) and glutamate decarboxylase 1 and 2 (GAD1, 2), with the axes of GAD2 with GRM1, 4 and 5 being always significantly associated with lower survival in endometrium and thyroid cancer tissues." (PMID 38723607, 2024).
triple-negative breast carcinoma (1 paper, 2025). An invasive breast carcinoma which is negative for expression of estrogen receptor (ER), progesterone receptor (PR), and human epidermal growth factor receptor 2 (HER2). "This study reveals one of the mechanisms underlying morphine-mediated metastasis of triple-negative breast cancer, specifically the reduction of the taurine biosynthesis enzyme GAD1." (PMID 40227606, 2025). "Through human triple-negative breast cancer dataset analysis, GAD1 expression is stage-dependent, with an initial increase and then decrease in stage IV, comparing metastatic versus non-metastatic cases." (PMID 40227606, 2025).
Usher syndrome (1 paper, 2025). A syndromic diseae characterized by the association of sensorineural deafness (usually congenital) with retinitis pigmentosa and progressive vision loss. "IGHV1-69D and GAD1 demonstrated statistically significant upregulation in Usher syndrome samples compared to controls (p < 0.05), while WNT5A and DIP2C exhibited a significant downregulation (p < 0.05)." (PMID 40723835, 2025). "According to our meta-analysis of transcriptomic data, IGHV1-69D and GAD1 are significantly upregulated, whereas WNT5A and DIP2C are significantly downregulated in Usher syndrome." (PMID 40723835, 2025).